FTO (FTO alpha-ketoglutarate dependent dioxygenase)
Diseases named in the same sentence as FTO in open-access papers (continued):
Sharing a sentence is not in itself a finding about the gene and the disease.
thyroid cancer (23 papers, 2017 to 2026). "This meta‐analysis indicates that FTO rs9939609 is linked to cancer susceptibility in the Asian population, while FTO rs1477196 is significantly relevant to thyroid cancer and an increased cancer susceptibility for Caucasians." (PMID 40391584, 2025). "FTO rs1477196 was correlated with an increased risk for thyroid cancer and remarkably relevant to an increased cancer susceptibility for Caucasians." (PMID 40391584, 2025). "Obesity-associated protein (FTO) prevents thyroid cancer progression by SLC7A11 m6A methylation in a ferroptosis-dependent manner." (PMID 38166898, 2024). "More importantly, the obesity-associated protein (FTO) can potentially suppress the progression of thyroid cancer by reducing the expression of xCT through N6 methyladenosine (m6A) modification." (PMID 39557844, 2024). "Fat mass and obesity-associated protein (FTO) was shown to be down-regulated in thyroid carcinoma which is responsible for suppressing proliferation, metastasis, and invasion." (PMID 38705513, 2024). "FTO expression is downregulated in thyroid cancer tissues, which is associated with lymph node metastasis in thyroid cancer patients." (PMID 33952279, 2021). "FTO rs8047395 was associated with the risk of thyroid cancer." (PMID 40391584, 2025). "FTO rs8047395 was remarkably associated with the risk of thyroid cancer." (PMID 40391584, 2025). "Additionally, it showed that FTO rs1477196 was notably related to susceptibility to thyroid cancer and an increased risk among Caucasians." (PMID 40391584, 2025). "This process is regulated by FTO to reduce the m6A modification level of APOE mRNA in thyroid cancer cells." (PMID 41522342, 2026). "On the other hand, a bioinformatic study supported by experimental validation in 30 cases indicates that FTO expression is low in thyroid cancer tissues and correlates with lymph node metastasis in thyroid cancer patients." (PMID 39329974, 2024). "To explore the role of FTO in thyroid cancer in vitro, we transfected the specific siRNA of FTO into thyroid cancer cell TPC1." (PMID 34281544, 2021). "We derived a three m6A RNA modification regulator genes-based risk signature (FTO, RBM15 and KIAA1429), that is an independent prognostic biomarker in patients with thyroid carcinoma." (PMID 34281544, 2021). "Similarly, the regulation of SCL7A11 by FTO was found to affect glutamine metabolism in thyroid cancer cells to protect the cells from ferroptosis." (PMID 41522342, 2026). "We found that FTO promotes the proliferation and inhibits metastasis in thyroid cancer cell lines." (PMID 34281544, 2021). "Recently, bioinformatic analysis has shown that FTO acts as anti-oncogene in thyroid cancer." (PMID 34281544, 2021). "In addition, we constructed a risk signature by using 3 m6A RNA methylation regulators (FTO, RBM15, and KIAA1429) and the risk score is an independent prognostic biomarker in patients with thyroid carcinoma." (PMID 34281544, 2021). "However, we found a significant association between FTO rs1477196 SNP and risk of thyroid cancer without (OR=1.31, 95%CI=1.07-1.61) or with (OR=1.32, 95%CI=1.08-1.62) adjustment for BMI." (PMID 28881622, 2017). "The over-expression of FTO-mediated m6A demethylation inhibits the expression of SLC7A11, thus facilitating ferroptosis in PTC and suppressing the growth of thyroid cancer." (PMID 35721711, 2022). "Immunohistochemistry result revealed that the staining intensity of 3 genes (RBM15, FTO, and KIAA1429) were higher in thyroid cancer tissue than in benign thyroid nodule tissue in our specimens which is consistent with bioinformatic analysis." (PMID 36389678, 2022). "In our study, we first verify the effect of FTO, RBM15 and KIAA1429 on the progression of thyroid carcinoma in vitro." (PMID 34281544, 2021).
thyroid cancer (continued). "We showed that METTL14, FTO, and ALKBH5 were down-regulated in most cancers, whereas YTHDF1 and IGF2BP3 were up-regulated in 12 cancer types except for thyroid carcinoma (THCA)." (PMID 33718187, 2021). "High expression of RBM15 (HR = 4.341, 95% CI = 1.328–14.192, P = 0.015), FTO (HR = 1.623, 95% CI = 1.021–2.580, P = 0.041) and KIAA1429 (HR = 1.925, 95% CI = 1.079–3.434, P = 0.026) had a poor overall survival in patients with thyroid carcinoma." (PMID 34281544, 2021).
polycystic ovary syndrome (20 papers, 2010 to 2025). A disorder that manifests as multiple cysts on the ovaries. "We conclude that the rs9939609 variant of FTO gene is significantly associated with hyperandrogenemia, acanthosis nigricans and the BMI among young Sri Lankan women with the well characterized phenotype manifesting from adolescence." (PMID 32050935, 2020). "FTO gene variant rs9939609 is associated with hyperandrogenemia and metabolic manifestations of PCOS among women of Sri Lankan descent with the well-characterized phenotype." (PMID 32050935, 2020). "Increasing evidence suggests the association of variants of FTO with hyperandrogenemia in PCOS patients." (PMID 32133054, 2019). "Many studies have investigated the relationship between FTO gene polymorphism and polycystic ovary syndrome (PCOS) susceptibility but revealed mixed results." (PMID 24466303, 2014). "Recent studies have revealed linkages between FTO variants and gestational diabetes, the polycystic ovary syndrome (PCOS) as well as the metabolic syndrome and hyperandrogenism in PCOS women." (PMID 22132335, 2011). "Hence, we propose that the FTO gene rs9939609 variant is indeed associated with hyperandrogenemia among Sri Lankan women with the well characterized phenotype of PCOS that manifests from adolescence." (PMID 32050935, 2020). "The results are also consistent with a study of the FTO variant in polycystic ovary syndrome." (PMID 26961502, 2016). "However, the association between the FTO gene and hyperandrogenemia remains equivocal." (PMID 32050935, 2020). "The FTO locus has previously been reported to be associated with affected androgen levels, polycystic ovary syndrome susceptibility and age at menarche in females while its impact on serum T and T-related diseases in men is unknown and warrants further investigations." (PMID 28448539, 2017). "The aim of this study was to assess the association between selected genetic polymorphisms (CYP19, MC4R, FTO, and INSR) and the clinical manifestations of polycystic ovary syndrome in Polish women." (PMID 40725495, 2025). "This study aimed to evaluate the association between selected gene polymorphisms (CYP19, INSR, FTO, MC4R) and polycystic ovary syndrome in a group of Polish women." (PMID 40725495, 2025). "In this section, we analyze the relationship between the occurrence of selected clinical symptoms of polycystic ovary syndrome and the presence of specific genetic polymorphisms in the CYP19, INSR, MC4R and FTO genes." (PMID 40725495, 2025). "Overexpression of FTO has a significant impact on the risk of PCOS, primarily by its role in increasing BMI and secondarily through subsequent metabolic derangement, including IR and hyperandrogenemia." (PMID 40486662, 2025). "By up-regulating FLOT2, FTO causes granulosa cell dysfunction, which raises the possibility that FTO/FLOT2 may be involved in the pathogenesis of polycystic ovarian syndrome (PCOS)." (PMID 38937660, 2024).
Alzheimer disease (19 papers, 2012 to 2025). A progressive, neurodegenerative disease characterized by loss of function and death of nerve cells in several areas of the brain leading to loss of cognitive function such as memory and language. "FTO genetic variants were also reported associated with a high risk of Alzheimer's disease and impaired brain functions." (PMID 28931651, 2017). "Keller found that FTO is associated with dementia-like Alzheimer’s disease (AD) risk, suggesting that FTO may interact with the AD-risk factor gene APOE." (PMID 34093133, 2021). "In animal studies, FTO can activate the phosphorylation of Tau, which is one of the markers of Alzheimer's disease (AD)." (PMID 36163017, 2022). "Besides, the NIA‐LOAD study identified a genetic variant in the FTO gene loci significantly associated with AD, and FTO expression was significantly lower in the cortex and amygdala tissues of AD patients compared with controls, suggesting the functional role of FTO in Alzheimer's Disease." (PMID 35718942, 2022). "FTO influences Alzheimer’s disease via the TSC1-mTOR-Tau signaling pathway." (PMID 39192357, 2024). "The overall m6A level was elevated in the cortex and the hippocampus of APP/PS1 (Alzheimer’s disease) mice compared to C57BL/6 control mice, and FTO was found to interact with APOE, which was associated with Alzheimer’s disease risk in a prospective cohort study." (PMID 36407103, 2022). "Consistently, the overall m6A level was elevated in the cortex and the hippocampus of APP/PS1 (Alzheimer’s disease) mice compared to C57BL/6 control mice, and FTO was found to interact with APOE, which is associated with Alzheimer’s disease risk in a prospective cohort study." (PMID 33611339, 2021). "In Alzheimer’s disease mouse models, the global m6A level was increased in the hippocampus and the cortex compared to C57BL/6 mice, and the interaction of FTO and APOE contributed to the increase in Alzheimer’s disease risk." (PMID 36407103, 2022). "Furthermore, the FTO-induced hypo-m6A levels have been shown to activate the TSC1-mTOR-Tau signaling pathway and increased apoptosis of dopaminergic neurons, which contributes to the pathogenesis of Alzheimer’s disease (AD) and Parkinson’s disease (PD), respectively." (PMID 33922187, 2021).
clear cell renal cell carcinoma (19 papers, 2019 to 2026). "Zhuang et al45 reported that low expression of obesity‐associated protein (FTO) in human clear cell renal cell carcinoma causes up‐regulation of m6A and is correlated with increased tumour severity and poor patient survival." (PMID 34164910, 2021). "In clear cell renal cell carcinoma, FTO restores mitochondrial activity and reduces oxidative stress, impairing tumor growth via the FTO-PGC-1α signaling axis." (PMID 41602161, 2026). "This implies that the role of FTO in clear cell renal cell carcinoma needs to be further investigated in depth." (PMID 39967906, 2025). "In clear cell renal cell carcinoma (ccRCC), FTO inhibits the presence and expression of von Hippel-Lindau (VHL) tumor suppressors, which limit tumor progression and progression by inhibiting FTO." (PMID 39033180, 2024). "There are also findings that demonstrated the downregulation of FTO playing an oncogenic role in intrahepatic cholangiocarcinoma and clear cell renal cell carcinoma, respectively." (PMID 32299393, 2020). "Similarly, FTO is also upregulated and closely related to autophagic flux in clear cell renal cell carcinoma, whereas FTO knockdown enhances autophagic flux and impairs tumor growth and metastasis." (PMID 37063421, 2023). "FTO expression was decreased in clear cell renal cell carcinoma (ccRCC) tissue samples." (PMID 36718644, 2023). "Moreover, FTO inhibits the tumor growth of clear cell renal cell carcinoma through decreasing the m6A level of PGC-1α mRNA." (PMID 37529797, 2022). "In clear cell renal cell carcinoma, FTO could inhibit tumour growth by reducing m6A levels in PGC-1α mRNA transcripts." (PMID 32299393, 2020). "However, the role of FTO in clear cell renal cell carcinoma (ccRCC) remains unclear." (PMID 35961973, 2022). "FTO, the eraser enzyme, has implications in mitigating mitochondrial and lipogenesis-induced ROS in HEK293T and clear cell renal carcinoma cells." (PMID 35327975, 2022). "Previous research has indicated that FTO promotes PDK1 expression by preventing the YTHDF2‐induced degradation of PDK1 mRNA via an m6A‐dependent mechanism, thereby facilitating the proliferation and migration of clear cell renal cell carcinoma." (PMID 39625183, 2024).
Hyperglycemia (17 papers, 2014 to 2026). An increased concentration of glucose in the blood. "In our study, we found a statistically significant association between the rs9939609/FTO and hyperglycemia." (PMID 34454619, 2021). "A significant association was observed between the rs9939609/FTO and hyperglycemia in the dominant model." (PMID 34454619, 2021). "The A/A genotype of the FTO rs9939609 polymorphism increases the risk of hyperglycemia, and the C/C genotype of the PPAR-γ rs1801282 variant entails elevated blood pressure in 45-60-year-old women." (PMID 29315078, 2018). "The A/A genotype of the FTO rs9939609 polymorphism increases the risk of hyperglycemia among women aged 45-60 years, and the C/C genotype of the PPAR-γ rs1801282 polymorphism involves higher blood pressure in this group." (PMID 29315078, 2018). "We established that in the recessive inheritance model, the FTO A/A genotype involved a higher risk of fasting hyperglycemia than the T/T-A/T genotypes." (PMID 29315078, 2018). "However, regarding FTO and T2D, the findings contrast with the recently published literature, which reported FTO rs9939609 as a risk factor for hyperglycemia and T2D." (PMID 39925495, 2025). "Women from Mayan communities of Chiapas presented a high prevalence of MetS and a relevant association of the FTO variant with hyperglycemia." (PMID 34454619, 2021). "Thus, leptin-deficient mice with FTO display a hyperglycaemia already early in life." (PMID 25144618, 2014). "To investigate the in vivo role of FTO in wound healing under chronic hyperglycemia conditions, we induced diabetic models in C57BL/6 WT mice with streptozotocin (STZ)." (PMID 40157922, 2025). "The role of FTO in inflammation is multifaceted and involves influencing m6A levels under stress conditions, such as hyperglycemia." (PMID 39980685, 2025). "We showed that enhanced FTO reduced the global level of m6A in hyperglycemia." (PMID 37781923, 2023). "In addition, Ad-FTO mice develop hyperglycemia, hyperinsulinemia and glucose intolerance, pointing thus a novel important role of FTO in the regulation of glucose metabolism." (PMID 24410832, 2014). "Thus, development of hyperglycaemia in Lepob/ob mice is depending on FTO." (PMID 25144618, 2014). "To support in vivo evidence for the functional role of FTO and TRIB3 in wound closure under consistent hyperglycemia, we established diabetic wound models with C57BL/6 mice." (PMID 40157922, 2025). "Lack of FTO reverses hyperglycemia and improves glucose tolerance in normal and obese/diabetic mice." (PMID 30388740, 2018). "Hepatic FTO mRNA levels are reduced in obese mice (agouti and ob/ob), possibly due to a negative influence by hyperglycemia and hyperinsulinemia." (PMID 30388740, 2018). "Thus, hyperglycaemia in Lepob/ob mice is a consequence of FTO activity and leads to a stronger increase of islet size in the pancreas compared to the Lepob/ob;Fto−/− mice." (PMID 25144618, 2014). "However, despite hyperglycemia all along the test, the response of glycemia to insulin injection (insulin tolerance test) was similar between both mice, suggesting that FTO overexpression in the liver did not impair peripheral insulin sensitivity." (PMID 24410832, 2014).
lymph node metastasis (17 papers, 2020 to 2025). "The upregulation of FTO was markedly associated with advanced nerve invasion, tumor size and lymph node metastasis (LNM)." (PMID 38956367, 2024). "The results of univariate COX analysis showed that the age, tumor stage, lymph node metastasis, and FTO expression level had an effect on the overall survival of EC patients." (PMID 35568876, 2022). "To investigate the relationship between FTO expression and clinicopathological parameters in PCa, we analyzed the UALCAN database and found that lower FTO expression was correlated with lymph node metastasis and a high Gleason score." (PMID 34787056, 2022). "Analysis of the relationship between FTO expression and clinicopathological features showed that expression of FTO was significantly negatively correlated with extrathyroidal extension (p = 0.004) and lymph node metastasis (p = 0.035)." (PMID 35090515, 2022). "Higher age, higher tumor stage, lymph node metastasis, and higher FTO expression were adverse factors for patient survival, which were consistent with the results of the KM curve analysis." (PMID 35568876, 2022). "Conversely, the expression levels of ALKBH5, ALKBH8 and FTO were lower than those in normal tissues at any stage of lymph node metastasis." (PMID 34150745, 2021). "Moreover, downregulation of FTO expression was significantly negatively correlated with extrathyroidal extension and lymph node metastasis." (PMID 35090515, 2022). "Furthermore, FTO were also correlated with tumor size, lymph node metastasis." (PMID 37861518, 2023). "Additionally, the FTO level in PCa patients at TNM stage I+ II was higher than that in patients at TNM stage III+IV, and patients with low FTO expression had a high tendency to suffer lymph node metastasis, which was further confirmed by bioinformatics websites." (PMID 34787056, 2022). "The results showed that FTO expression was higher in patients with advanced TNM stages (III-IV), deeper local invasion, lymph node metastasis, liver metastasis, and vascular invasion in gastric cancer." (PMID 39331892, 2024). "Lymph node metastasis, chemotherapy, and EGFR status significantly differed depending on ALKBH5 expression, whereas tumor status, lymph node metastasis, pathological stage, chemotherapy, and EGFR status significantly differed depending on FTO expression." (PMID 35318440, 2022). "The expression of METTL3, METTL14, WTAP, YTHDC2, YTHDF1, and YTHDF2 was remarkably higher in CRPC with lymph node metastasis than in CRPC with bone metastasis, whereas ALKBH5, FTO, and YTHDF3 were substantially decreased in CRPC with lymph node metastasis." (PMID 33403026, 2021). "Increased FTO is closely related to poor differentiation, lymph node metastasis, TNM stage and an unfavourable prognosis, and the down‐regulation of FTO inhibits the proliferation, invasion and metastasis of GC cells." (PMID 33029866, 2020). "Patients with lymph node metastases N1 and N2 also displayed heightened FTO expression levels compared to those without metastases and the average population." (PMID 39820532, 2025). "We divided the EC patients into two groups based on the median of FTO expression level; the statistical results showed that only lymph node metastasis was related to the expression level of FTO (P < 0.05), whereas the other variables had no statistical differences (P > 0.05)." (PMID 35568876, 2022).